ZBTB16 (zinc finger and BTB domain containing 16)
Diseases named in the same sentence as ZBTB16 in open-access papers (continued):
Sharing a sentence is not in itself a finding about the gene and the disease.
dry eye (1 paper, 2025). "While these results are based on a rat corneal injury model and require confirmation in human studies, they suggest that JAK1, SKI, and ZBTB16 could represent candidate biomarkers for future diagnostic assays or targets for immunomodulatory therapy in dry eye." (PMID 40940727, 2025). "Upregulation of key mediators, such as JAK1, SKI, and ZBTB16, paralleled increased IL-6, IL-1β, and TNF-α expression, implicating innate immune activation in dry eye pathogenesis." (PMID 40940727, 2025).
endometrial cancer (1 paper, 2018). Primary or metastatic malignant neoplasm involving the endometrium (mucous membrane that lines the endometrial cavity). "AR target genes such as XBP1, MYC, ZBTB16, and UHRF1 were previously reported to be induced by DHT treatment in AR-positive endometrial cancer MFE-296 cells." (PMID 29642629, 2018).
esophageal cancer (1 paper, 2021). A primary or metastatic malignant neoplasm involving the esophagus. "Survival univariate/multivariate COX analysis revealed that five genes, ZBTB16, AQP4, ADCYAP1R1, PDGFD, and VIPR2, and two microRNAs, miR-99a-5p, and miR-508-5p, were related to esophageal cancer prognosis." (PMID 34329340, 2021).
Hepatic failure (1 paper, 2023). "On the other hand, liver cirrhosis, fatty liver, and hepatic failure phenotypes were associated with variants in NAB1, CALD1, ZBTB16, GAN, TEMD3, and/or PRDM15 genes." (PMID 37664632, 2023).
Hernia (1 paper, 2025). "Zbtb16 has not been studied in skeletal muscle, but further investigation could offer insight into its role as a mediator of LAM fibrosis and as a possible age-related risk factor for hernia development." (PMID 40504614, 2025).
Hyperkeratosis (1 paper, 2023). Hyperkeratosis is a histopathological term defining a thickened stratum corneum and may be present in many different skin conditions, with many possible overlaps. "The hyperkeratosis and a neutrophil infiltrate, with the related MPO release, that is induced in the skin of Nlrp3R258W mice with this treatment was significantly attenuated by ablating Zbtb16." (PMID 38123560, 2023).
injury (1 paper, 2023). Damage inflicted on the body as the direct or indirect result of an external force, with or without disruption of structural continuity. "Zbtb16, on the other hand, was reported to be involved in neuronal differentiation in Zebrafish and exerted neuroprotective effect after nerve injury in mice." (PMID 37629120, 2023).
lupus nephritis (1 paper, 2024). Glomerulonephritis in the context of systemic lupus erythematosus. "In the comparison of 62 subgroups, the up-regulated gene (PTPRC, MX1) and the down-regulated DEGs (EGR1, MME, RORC, ZBTB16, FKBP5) were verified to have mostly consistent change trends in all Lupus Nephritis vs. Normal Kidneys group with the results of GSE200306." (PMID 39301055, 2024).
Muckle-Wells syndrome (1 paper, 2023). "The physiological significance of this activity is demonstrated through the reduction of acute inflammatory pathogenesis caused by a constitutive hyperactive inflammasome by ablating ZBTB16 in a mouse model of Muckle-Wells syndrome." (PMID 38123560, 2023). "The impact of this mechanism is tested in cell lines and in vivo with specific inflammatory stimuli using constitutive and targeted Zbtb16 mutant animals as well as a mouse model of Muckle-Wells syndrome that has a hyperactive inflammasome." (PMID 38123560, 2023). "This is underscored by our demonstration that targeting ZBTB16 limits pathogenesis in a mouse model of Muckle-Wells syndrome, which is driven by a hyperactive mutant NLRP3." (PMID 38123560, 2023).
myelodysplastic syndrome (1 paper, 2022). A clonal hematopoietic disorder characterized by dysplasia and ineffective hematopoiesis in one or more of the hematopoietic cell lines.
myeloid malignancies (1 paper, 2017). "Additional mutations potentially cooperating with the translocation fusion product in leukemogenesis have been hitherto unreported in ZBTB16-RARA APL and were sought by application of a next-generation sequencing approach to detect those recurrently found in myeloid malignancies." (PMID 28529810, 2017).
myocardial infarction (1 paper, 2025). Gross necrosis of the myocardium, as a result of interruption of the blood supply to the area, as in coronary thrombosis. "We then observed that accounting for cardiomyocyte abundance reduced the differences in spatial expression both Zbtb16 and Pik3r1 between cmAKO and WT mice during myocardial infarction." (PMID 40705823, 2025).
osteoarthritis (1 paper, 2025). A noninflammatory degenerative joint disease occurring chiefly in older persons, characterized by degeneration of the articular cartilage, hypertrophy of bone at the margins and changes in the synovial membrane. "GR activation can result in a potent increase in ZBTB16 expression, as evidenced both in primary CECs and clinical samples from osteoarthritis patients." (PMID 40540650, 2025). "Finally, ZBTB16 protein was strongly induced by dexamethasone in fibroblast-like synoviocytes derived from osteoarthritis patients." (PMID 40540650, 2025). "ZBTB16 may be relevant in the setting of glucocorticoid therapy, given that its presence in the cells derived from osteoarthritis patients was dependent solely on dexamethasone treatment." (PMID 40540650, 2025). "To test whether ZBTB16 protein induction by glucocorticoids can occur in a clinically relevant cell population, we used available FLS derived from four osteoarthritis patients." (PMID 40540650, 2025).
pregnancy disease (1 paper, 2015). "However, a clear effect of harvesting ZBTB16 to the cytoplasm when the NLRP7 protein is overexpressed may be linked to the pathology of the molar pregnancy disease." (PMID 26121690, 2015).
rheumatoid arthritis (1 paper, 2025). A chronic, systemic autoimmune disorder characterized by inflammation in the synovial membranes and articular surfaces. "Finally, GR-mediated induction of ZBTB16 protein in synovial fibroblasts from rheumatoid arthritis patients suggested that ZBTB16 induction can play a role in a clinically relevant cell type." (PMID 40540650, 2025).
Sepsis (1 paper, 2018). Sepsis is defined as life-threatening organ dysfunction caused by a dysregulated host response to infection. "Gene ontology of these 23 common DEGs showed that apoptotic process (TRAF1, TNFRSF9, ADORA2A, ZBTB16), negative regulation of transcription (SAP30, TSC22D3, ETS2, ZBTB16), and inflammatory response (TNFRSF9, CCL3, ADORA2A) are the main biological processes affected by sepsis treatment." (PMID 30086151, 2018).
teratoma (1 paper, 2025). A non-seminomatous germ cell tumor characterized by the presence of various tissues which correspond to the different germinal layers (endoderm, mesoderm, and ectoderm). "The researchers tested approaches for the identification of pluripotency and malignancy of PSC, and they used the combination of OCT4 (EC vs. YSE and teratoma), SALL4 (positive for YSE and EC), and ZBTB16 (YSE vs. EC and teratoma)." (PMID 40650246, 2025). "The marker Zinc finger and BTB domain-containing protein 16 (ZBTB16, also known as PLZF) is highly sensitive for YST, staining all morphologies of YST, as well as specific, staining negative for all other GCT, including teratoma and EC." (PMID 40650246, 2025).
uterine tumors (1 paper, 2021). "Given the visible association between high methylation concurrence in promoter regions and reduced gene expression, these results suggest that ZBTB16 may also act as a tumor suppressor in uterine tumors, although additional functional studies are needed to test this hypothesis." (PMID 34489442, 2021).
tumor (78 papers, 2009 to 2026). "In the integrated genomic and transcriptome analyses, the tumor-associated genes ZBTB16, PPARG, and TGFBR2 were found to be significantly downregulated with simultaneous CNV loss." (PMID 33414372, 2021). "Three tumor-associated genes, zinc finger and BTB domain-containing 16 (ZBTB16), peroxisome proliferator activated receptor gamma (PPARG), and transforming growth factor beta receptor 2 (TGFBR2), were downregulated with copy number variation (CNV) loss." (PMID 33414372, 2021). "ZBTB16 represses transcription and is associated with tumor progression." (PMID 36531045, 2022). "Interestingly, one of the affected enhancers was found to interact with the TSS of ZBTB16, a well-known AR-regulated tumor suppressor that is commonly mutated in CRPC." (PMID 33975627, 2021). "A decreased number of gene copies was also widely observed in EBV(+) LCs, including tumor-associated genes such as zinc finger and BTB domain-containing 16 (ZBTB16), peroxisome proliferator activated receptor gamma (PPARG), and transforming growth factor beta receptor 2 (TGFBR2)." (PMID 34064727, 2021). "The ability of this strategy to both re-identify known metastasis susceptibility genes (e.g., Cadm1) and validate novel tumor progression genes (e.g., Pvrl1, Zbtb16) is consistent with this hypothesis." (PMID 27074153, 2016). "Previous reports have demonstrated that ZBTB16 is under-expressed or silenced in multiple tumor tissues or various cancer types, including HCC." (PMID 39182119, 2024). "This showed that compared with normal tissue, the mRNA expression level of ZBTB16 in tumor samples was downregulated significantly." (PMID 39182119, 2024). "According to GEPIA database, ZBTB16 exhibited low-expression in tumor tissue and was positively correlated with LINC00930." (PMID 38789960, 2024). "The IHC analysis of tissue microarrays demonstrated that ZBTB16 expression staining was mainly located at cytosol of tumor cells." (PMID 37803446, 2023). "Comparing tumor free tissue with controls showed higher expression of CIDEC, MUC1 and ZBTB16 in the majority of tumor free samples." (PMID 28038473, 2017). "Tumor weights from Zbtb16+/- animals were not significantly different compared to tumors from their wild type littermates (p = 0.82) indicating the effect of Zbtb16 was unlikely due to differences in tumor cell proliferation." (PMID 27074153, 2016). "Like Txnip and Zbtb16, Timp3 has tumor-suppressive properties, and its expression limits tumor invasiveness and has been correlated with survivorship in cancer patients." (PMID 19968875, 2009). "Our observation that m6A methylation of ZBTB16-derived circRNA is increased in TNBC suggests that this modification may alter the gene’s typical tumor-suppressive functions, contributing to the aggressive phenotype of this subtype." (PMID 41516402, 2026). "A recent study also indicated ZBTB16 played a tumor suppressor role in cancer." (PMID 41431699, 2025). "Likewise, tobacco smoke exposure of WT male mice resulted in two to threefold induced expression of tumor suppressors, notably Acer2, Lbh and Zbtb16, and are reported to inhibit tumor growth and to induce apoptosis in LC." (PMID 38245882, 2024). "ZBTB16 is also a transcript factor for CYR61 a critical marker of tumor cell inflammation." (PMID 39468655, 2024). "According to the experimental results in vivo and in vitro, we speculated that PPI promotes the combination of RXRα and PPARγ by targeting ZBTB16, leading to the inhibitory effect on the malignant phenotype of tumor cells." (PMID 39182119, 2024). "It was found that the combined therapy with pyrotinib and chrysin apparently increased ZBTB16 level in tumor tissues; this effect could be reversed by miR-16-5p overexpression via its mimics, which is in high accordance with the results of in vitro assays." (PMID 38110365, 2023).
tumor (continued). "In this way, autoinflammatory disorders might be suppressed by inhibiting ZBTB16 or, on the other hand, anti-tumour immunity might be advanced by pharmacologically promoting ZBTB16 activity." (PMID 38123560, 2023). "ZBTB16 has been proved to be beneficial for tumor suppression as it represses c-myc oncogene." (PMID 34802056, 2021). "ZBTB16 functions as a tumor suppressor through upregulating ZBTB28 and antagonizing BCL6." (PMID 32517789, 2020). "Since ZBTB16, ZBTB28, and BCL6 were associated with tumor metastasis, replenishment Transwell assays were used to confirm our hypothesis." (PMID 32517789, 2020). "The tumor suppressor genes were ZBTB16, MAL, LIFR, and SLIT2." (PMID 33193630, 2020). "The candidate tumor suppressor genes were ZBTB16, MAL, LIFR, and SLIT2." (PMID 33193630, 2020). "E2F1 and ZBTB16 have been proved to belong to tumor-suppressive genes." (PMID 33083112, 2020). "Moreover, scRNA-seq results identified novel tumor suppressor genes (ZFP36, BTG1, DLG5, and ZBTB16), cell apoptosis-inhibitor genes, genes with pro-tumoral functionality (C1Q in TAMs), and many cell cluster-specific genes, including tumor and stromal cell-specific marker genes." (PMID 39114291, 2024). "Therefore, ZBTB16 has shown tumor suppression activity in cancer." (PMID 36101460, 2022). "ZBTB16 (also known as promyelocytic leukemia zinc finger protein, PLZF) encodes a zinc finger transcription factor that regulates embryonic development of the skeletal and central nervous systems, and spermatogenesis; it has also been associated with apoptosis and tumor repression." (PMID 19196461, 2009). "The most downregulated genes contained known tumor suppressors (ZNF831, AKNA, NR4A1, ARHGAP9, ZBTB16) and regulators of immune response (NLRC5, WDFY4, RASGRP2, IKZF1)." (PMID 39794830, 2025). "In line with the in vitro results, ZBTB16 and PPARγ, RXRα protein levels were both increased, which confirmed that PPI effectively inhibits tumor growth by targeting ZBTB16 to activate the PPARγ/RXRα signaling pathway." (PMID 39182119, 2024). "In the IHC assays, PPI enhanced ZBTB16 but strongly suppressed the Ki-67, indicating that PPI contributed to the major effect on tumor cell survival." (PMID 39182119, 2024). "Some ZBTB members can function as vital proto-oncogenes such as ZBTZ27, ZBTB71, while others exert tumour suppressive roles, including ZBTB29, ZBTB28 and ZBTB16." (PMID 35993275, 2022). "Among the top dysregulated genes when comparing control and tumor free tissue were those involved in apoptosis (CIDEC, MUC1, ZBTB16, PRNP, ECT2), immune response (IFI27) and differentiation (KRT36)." (PMID 28038473, 2017). "Cluster3 of both subsets (which we refer to as NK-innate-likeCD28− and CD28+, respectively), represented in peripheral blood and reduced at the tumor site, were characterized by the expression of NK-like markers KLRB1, KLRC3, and KIR2DL1, along with IKZF2 and ZBTB16 (PLZF)." (PMID 37898752, 2023). "In the TCGA-UCEC dataset, APOBEC3G, CUL4B, SCML2, TSPYL5, and ZBTB16 were significantly downregulated in tumor samples, whereas FOXP3, HJURP, HMGB3, and RAC3 were significantly upregulated in tumor samples, which was generally consistent with the result observed in GSE17025." (PMID 36936912, 2023). "Based on our data, we presented a hypothetical model that ZBTB16 might form complexes with ZBTB28 and BCL6, respectively, and function as a tumor suppressor through inhibition of BCL6 and promotion of ZBTB28." (PMID 32517789, 2020). "Furthermore, ectopically expressed ZBTB16 formed heterodimers with ZBTB28 or BCL6/ZBTB27 and exerted tumor suppressor effects through upregulation of ZBTB28 and antagonistic activity on BCL6." (PMID 32517789, 2020). "Since DAPK1 expression was correlated with expression of SCL16A3, POLOCE and ZBTB16, while the expression levels of these genes were significantly differentially expressed in non-tumor and tumorous liver specimens." (PMID 28740751, 2017).
tumor (continued). "Thus, aberrant m6A modification of ZBTB16 circRNA in TNBC may reprogram its regulatory output, promoting tumor progression and resistance to therapy." (PMID 41516402, 2026). "However, dysregulated m6A methylation of ZBTB16 circRNA in TNBC may disrupt this regulatory axis, potentially stabilizing or enhancing translation of oncogenic transcripts rather than mediating tumor suppression." (PMID 41516402, 2026).